USH2A (usherin)
Diseases named in the same sentence as USH2A in open-access papers (continued):
Sharing a sentence is not in itself a finding about the gene and the disease.
Usher syndrome type 2 (49 papers, 2011 to 2026). "The identification of USH2A mutations in some patients supports this possibility, as this gene is a major cause of Usher syndrome type 2." (PMID 41562913, 2026). "The primary nonsense mutations in the USH2A gene, associated with Usher syndrome type 2 (USH2), include variants that introduce premature stop codons, leading to a truncated, nonfunctional protein." (PMID 40474765, 2025). "Usher syndrome type 2 is the most common form (accounting for about two-thirds of patients), and up to 85% of cases are caused by pathogenic variants in the USH2A gene (OMIM:*608400)." (PMID 39596236, 2024). "Three genes have been associated with Usher Syndrome type 2: USH2A, ADGRV1, and WHRN, which together comprise the periciliary membrane complex at the junction between the inner and outer photoreceptor segment." (PMID 37108761, 2023). "A noteworthy feature of this study is represented by a peculiar enrichment in patients affected by Usher syndrome type 2, carrying biallelic variants in the USH2A (4/7) and ADGRV1 (3/7) genes." (PMID 36979683, 2023). "Non-canonical splice site variants are increasingly recognized as a relevant cause of the USH2A-associated diseases, non-syndromic autosomal recessive retinitis pigmentosa and Usher syndrome type 2." (PMID 36362125, 2022). "Genetic testing confirmed biallelic pathogenic variants in USH2A among all participants, which clinically manifested as Usher syndrome type 2 (USH2) in 14 patients and NSRP in two patients." (PMID 35457016, 2022). "An effect on pre-mRNA splicing has been experimentally confirmed for several variants in the USH2A gene, which is associated with autosomal recessive retinitis pigmentosa (arRP) and Usher syndrome type 2 (USH2), including pathogenic deep-intronic variants." (PMID 36362125, 2022). "One promising CAPD-risk gene is USH2A, which is clinically associated with Usher syndrome type 2 (USH2;)." (PMID 33498833, 2021). "Although numerous variants in the USH2A gene were reported, as much as 84% of the Slovenian patients with Usher syndrome type 2 had the NM_206933.4:c.11864G>A (p.Trp3955Ter) variant." (PMID 32937936, 2020). "Mutations in USH2A are responsible for both Usher syndrome type 2 and nsRP, which are distinguished by impaired and preserved hearing function, respectively." (PMID 33121974, 2020). "In the present study, among the 10 familial cases with mutations in USH2A, eight had an associated sensorineural hearing loss and were diagnosed as Usher syndrome type 2." (PMID 31877679, 2019). "Mutations of the USH2A gene are the most common cause of RP and are found in around 10–15% of recessive RP and 30–40% of Usher syndrome type 2 cases." (PMID 31481876, 2019). "Mutation in USH2A is the most frequent cause of recessive retinitis pigmentosa (RP) as well as Usher syndrome type 2 (USH2)." (PMID 31766479, 2019). "Further upstream, the most prevalent c.2299delG mutation in the USH2A gene, responsible for Usher syndrome type 2, was corrected in patient's fibroblasts using CRISPR/Cas9 and HDR." (PMID 29853845, 2018). "Mutations in the USH2A gene on chromosome 1q41, which encode usherin, are the most common mutations and account for up to 85% of Usher syndrome type 2 cases." (PMID 21738395, 2011). "In addition, mutations in the USH2A gene are causing Usher syndrome type 2 only in the homozygous state." (PMID 39416683, 2024). "Mutations in the USH2A gene are the most common cause of Usher syndrome type 2 (USH2)." (PMID 37893030, 2023). "Additionally, a peculiar finding of this study is represented by the overall identification of seven patients (7/102—6.9%) affected by Usher syndrome type 2 due to biallelic variants in the USH2A (4/7) and ADGRV1 (3/7) genes." (PMID 36979683, 2023). "The study was based on human clinical evidence that homozygous mutations of USH2A result in Usher syndrome type 2, as well as recent evidence that heterozygous USH2A mutations may be a genetic risk factor for CAPD." (PMID 33498833, 2021).
Usher syndrome type 2 (continued). "Genotype–phenotype correlations for Usher syndrome type 2 (USH2) suggest that the USH2A gene exhibits an allelic hierarchy." (PMID 37981655, 2023). "In contrast to USH2A, variants in ADGRV1 are a minor cause of Usher syndrome type 2, and the associated phenotype is less known." (PMID 34638692, 2021). "The majority of patients with Usher syndrome type 2 have causative variants in the USH2A gene, encoding usherin involved in the function of photoreceptors and cochlear hair cells." (PMID 32937936, 2020). "Although USH2A and GPR98 (which underly Usher syndrome type 2) mutations were great in number, this is to be expected based on the extremely large size of the gene." (PMID 23967202, 2013). "We identified five heterozygous pathogenic variants in the USH2A gene in Chinese patients diagnosed with Usher syndrome type 2, two of which were not reported." (PMID 32093671, 2020). "USH2A mutations have been implicated in the disease etiology of several inherited diseases, including Usher syndrome type 2 (USH2), nonsyndromic retinitis pigmentosa (RP), and nonsyndromic deafness." (PMID 25133613, 2014). "Three genetic loci have been reported so far in Usher syndrome type 2 (USH2A, USH2C, and USH2D)." (PMID 21738395, 2011). "Biallelic variants in the USH2A gene cause either Usher syndrome type 2 (USH2) or non-syndromic RP." (PMID 36034145, 2022). "Mutations in USH2A, are responsible for Usher syndrome type 2 and non-syndromic RP57." (PMID 30337596, 2018).
deafness (43 papers, 2008 to 2025). An inherited or acquired condition characterized by the complete loss of the ability to hear from one or both ears. "We conclude that G103R disrupts quaternary USH2 protein complex assembly and phase separation by eliminating the interaction between PDZD7 and USH2A, which may be one of the mechanisms underlying deafness." (PMID 36964137, 2023). "Although not identified so far, protective modifiers of USH2A-associated disease might exist and similar mechanisms as described for SMA and deafness could protect against USH2A c.2276 G > T-associated arRP." (PMID 35672333, 2022). "Further efforts are needed to analyze other frequent deafness-predisposing genes, such as TMC1, USH2A, CDH23 and MYO15A in an expanded panel in future studies." (PMID 36389375, 2022). "Those in TMC1, CDH23, LOXHD1 and USH2A were each detected in two probands, and those in 10 other deafness genes were each detected in one proband." (PMID 35062939, 2022). "Among them were four genes associated with deafness [grainyhead like transcription factor 2 (GRHL2), BCL2 like 11 (BCL2L11), ELMO domain containing 3 (ELMOD3), usherin (USH2A)]." (PMID 32835229, 2020). "Three known deafness genes, including SMPX, USH2A, and ILDR1, were identified, in which the variants in SMPX and USH2A were predicted to have a high‐to‐medium high impact on the function." (PMID 31478598, 2019). "Two homozygous c.5933_5940del and 5950_5960dup mutations in USH2A were detected in patient TO19, whose deafness onset was recorded when he was 11 months old and whose visual symptoms were noticed only later when he was 17 years old." (PMID 29142287, 2017). "Bi-allelic mutations in 15 less commonly screened deafness genes were identified in 28 deaf probands, with mutations in MYO15A, GPR98, TMC1, USH2A and PCDH15 being relatively more frequent (≥3 probands each)." (PMID 23767834, 2013). "In the Western Romanian population studied, the risk of deafness is given by pathogenic variants in 7 genes included in the panel: GJB2, USH2A, LOXHD1, SLC26A4, USH1C, COL4A4, COL4A3, present in almost 10% of the cohort, therefore representing a significant risk." (PMID 41303398, 2025). "A case report of two siblings carrying the same USH2A mutations displayed surprising clinical heterogeneity; one sibling was diagnosed with Usher syndrome 2 while the second sibling had completely preserved visual function, which was the first reported USH2A-related non-syndromic deafness." (PMID 33121974, 2020). "However, only single heterozygous variant in USH2A and ILDR1 was identified, thus, the single variant cannot cause deafness in the patient." (PMID 31478598, 2019). "A homozygous c.5933_5940del;5950_5960dup in USH2A was detected in one patient with early deafness." (PMID 29142287, 2017). "In addition, mutations in three corresponding genes (usherin USH2A, G protein-coupled receptor 98; GPR98, and deafness, autosomal recessive 31; DFNB31) have been reported so far in USH2, and USH3 is caused by mutations in the clarin 1 (CLRN1) gene." (PMID 24618850, 2014). "In addition, mutations in USH2A have been reported in causing nonsyndromic RP and nonsyndromic deafness, further indicating the clinical heterogeneity for USH causative mutations." (PMID 24831256, 2014). "Despite the genetic heterogeneity, some genes showed greater contribution to cases of autosomal recessive deafness in our study: GJB2, CDH23 (10.34%), MYO15A (7%), OTOF (7%), and USH2A (7%)." (PMID 39498320, 2024). "Therefore, these variants of USH2A were excluded as causative deafness mutations." (PMID 27057829, 2016). "The most frequent causative gene revealed by this technology was CDH23 (n = 3), followed by MYO15A (n = 2), MYO7A (n = 2) and other four deafness genes (PCDH15 (n = 1), USH2A (n = 1), MYO3A (n = 1) and ACTG1 (n = 1))." (PMID 25373420, 2014).
deafness (continued). "We found that A64D and R223H on WHRN, although not affecting binding to USH2A or ADGRV1, cause deafness by disturbing WHRN dimerization and disrupting phase separation of USH2 condensates." (PMID 36964137, 2023). "USH2A-CT(S) binds to WHRN NPDZ12 T110A with a weaker binding affinity (Kd = ~16 μM) than that of the WT (Kd = ~2.7 μM), which may contribute to deafness." (PMID 36964137, 2023). "In addition, mutations in MYO7A, USH1C, DFNB31, CIB2, CDH23 and PCDH15 were also reported in non-syndromic deafness without retinal degeneration and mutations in USH2A and CLRN1 have been reported in patients with isolated RP or retinal dystrophies and no deafness." (PMID 25211151, 2014).
retinal degeneration (40 papers, 2007 to 2026). Degeneration of the retina. "Pathogenic variants in the USH2A gene are the primary cause of both non-syndromic autosomal recessive inherited retinitis pigmentosa (RP) and the syndromic form, characterized by retinal degeneration and sensorineural hearing loss." (PMID 39596236, 2024). "–8 USH2A knockout (KO) mice suffer from hearing loss, but only manifest weak and very late-onset retinal degeneration phenotype." (PMID 36795064, 2023). "Our research builds upon these foundational studies to further advance our knowledge of USH2A-associated retinal degeneration." (PMID 38086867, 2023). "These ERG and GVF results reveal that patients with USH2A-related RP who have truncated alleles tend to exhibit more severe functional retinal degeneration." (PMID 37981655, 2023). "A spontaneous mutant USH2 mouse model (kunming) showed early-onset retinal degeneration, but harbored mutations in two genes implicated in inherited retinal dystrophies: Ush2a and Pde6b." (PMID 34201633, 2021). "As previously published for USH2A-associated retinal degeneration, proof of concept of exon-skipping therapy obtained in zebrafish has high translational value." (PMID 34502064, 2021). "Following the observed decrease in retinal function and retinal degeneration in ush2au507 zebrafish, the molecular defects resulting from loss of usherin function were further examined." (PMID 31998945, 2020). "Few studies have been conducted on the visual prognosis and genotype–phenotype correlations in retinal degeneration arising from USH2A mutations." (PMID 31904091, 2020). "In the replication cohort of 84 patients with recessive retinal degeneration (syndromic and nonsyndromic), 25 additional probands with two likely disease-causing USH2A variants were identified." (PMID 25649381, 2015). "To gain insight into the molecular pathology of retinal degeneration resulting from USH2A mutations, we aimed to determine the retinal repertoire of USH2AisoB-interacting proteins." (PMID 23351521, 2012). "To gain insight into the molecular pathology underlying USH2A-associated retinal degeneration, we aimed to identify interacting proteins of USH2A isoform B (USH2AisoB) in the retina." (PMID 23351521, 2012). "In summary, we have generated structural models for various domains of usherin, a major causative protein in inherited retinal degeneration and sensorineural hearing loss, using homology modeling and sequence- and structure-based threading with ab initio building." (PMID 32637036, 2020). "USH2A-associated retinal degeneration in humans has a slow and progressive pathology." (PMID 31481876, 2019). "Given that novel antisense oligonucleotide therapies have been shown to rescue retinal degeneration caused by USH2A splicing pathogenic variants, these solved USH2A patients may now be eligible to be enrolled in therapeutic trials." (PMID 31046701, 2019). "There are several USH2A mutant zebrafish models that exhibit early onset retinal degeneration as well as a recent model that displays slower, progressive retinal degeneration." (PMID 38086867, 2023). "None of the pathogenic mutations in genes related to congenital retinoschisis (RS1) or retinal degeneration (USH2A, ABCA4, PDE6A, PDE6B, RPE65, etc.)were detected by targeted exome sequencing or WGS." (PMID 36980859, 2023). "The zebrafish ush2a knock-out also recapitulated the auditory abnormalities and later onset of retinal degeneration characteristic of USH2 patients." (PMID 34201633, 2021). "Although retinal degeneration has been reproduced in Ush2a-null mice, a high phenotypic discrepancy has been described when comparing human patients and other Usher mutant mice." (PMID 33121974, 2020). "Novel therapies that target USH2A show great promise as retinal degeneration in USH2A patients can be rescued using antisense oligonucleotide-based therapy targeting cryptic splicing variants." (PMID 31046701, 2019).
retinal degeneration (continued). "Of 47 probands with nonsyndromic USH2A-related retinal degeneration (all three cohorts), only 5 had apparent biallelic ‘null' variants (this is the exception due to c.12295-3 T>C)." (PMID 25649381, 2015). "We identified a total of nine causal mutations, including six novel variants in RPE65, LCA5, USH2A, CNGB1, FAM161A, CERKL and GUCY2D as the underlying cause of inherited retinal degenerations in 13 of 26 pedigrees." (PMID 26352687, 2015). "These genes include those that encode proteins associated with Usher (USH1G, USH2A) and Bardet-Biedl syndromes (BBS10); both are genetic human diseases of the cilia with wide ranging symptoms including retinal degeneration." (PMID 20939902, 2010). "To date, knockout of Usher gene product has been largely unsuccessful in generating animal models with a retinal degeneration phenotype in mice, with only the Usherin null (Ush2a) mouse demonstrating a significant disease." (PMID 19680541, 2009). "Several mouse models of Usher syndrome types I and II have been characterized, with only the Usherin null (Ush2a) mouse demonstrating a significant retinal degeneration phenotype." (PMID 19680541, 2009). "Additionally, it is noteworthy that USH2A-related retinal dystrophies often initiate retinal degeneration from the peripheral retina, resulting in macular involvement occurring later in life." (PMID 38879497, 2024). "For inherited retinal degenerations caused by point mutations in large genes not amenable to single-adeno-associated viral (AAV) gene therapy such as USH2A and ABCA4, correcting RNA offers an alternative to gene replacement." (PMID 31991730, 2020). "Potential therapeutic strategies can be divided in two main types: USH2A-targeted therapy, which manipulate levels of USH2A; and USH2A-independent therapy, which aims to prevent retinal degeneration through targeting common disease pathways such as cell death or oxidative stress." (PMID 33121974, 2020). "Accordingly, only Ush2a-null and Whirlin-null mutant mice displayed obvious retinal degeneration." (PMID 33121974, 2020). "In mice, usherin ΔE12 protein is able to fully function in cochlear hair cells, while its function in photoreceptors has not been clearly demonstrated, because the Ush2a null mice as a baseline control have a very weak retinal degeneration phenotype." (PMID 32637036, 2020). "In addition, ush2a knockout zebrafish have been generated successfully and these exhibit auditory abnormalities and retinal degeneration, replicating the disease phenotypes of human USH2A patients." (PMID 33193648, 2020). "In Ush2a null mice, first evidence of retinal degeneration was observed at 20 months of age." (PMID 31998945, 2020). "Consistent with the phenotype observed in the cohort of patients analyzed in this study, the RPE65, LCA5, USH2A, CNGB1, FAM161A, CERKL and GUCY2D genes consisting mutations in 13 of the 26 pedigrees have been implicated in causing recessive non-syndromic retinal degeneration." (PMID 26352687, 2015). "There were no instances of two plausible disease-causing variants in a gene previously associated with RP, but two human retinal degeneration genes (ABCA4 and USH2A) each harbored a single plausible disease-causing variant (Thr1428Met ACG>ATG and Arg4192His CGC>CAC, respectively)." (PMID 23991284, 2013). "The Ush2a mutant mouse exhibits a very slow, late-onset retinal degeneration." (PMID 19680541, 2009). "Mutations in USH2A are the most frequent cause of recessive retinal degeneration in this population with four pedigrees from the current study (RF.VI148.1215, RF.VI145.1215, RF.VI129.0714, and RF.VI127.0514) and two additional pedigrees from our previous studies with causative mutations in USH2A." (PMID 34662339, 2021). "In addition, a Ush2a knock-out mouse presented only mild late-onset retinal degeneration." (PMID 34201633, 2021). "It remains unclear as to why mutations in USH genes other than Usherin do not result in a retinal degeneration phenotype in mice." (PMID 19680541, 2009).
retinal degeneration (continued). "However, USH2A mutant retinal degeneration might also undergo some early pathological changes." (PMID 31481876, 2019). "Ush2a−/− knockout mice with a deletion of exon 5 demonstrate a lack of retinal usherin expression and develop late-onset slowly progressive retinal degeneration and dysfunction." (PMID 39922978, 2025). "This discrepancy is problematic, as the retinal degeneration phenotype is typically very weak or absent among USH2A knockout mouse models." (PMID 38086867, 2023). "The cDNA for genes such as ABCA4 and USH2A do not fit in a single AAV, and in the USA mutations in these two genes account for 25% of families with inherited retinal degeneration." (PMID 31991730, 2020). "However, Ush2a knockout mice lacking usherin do show convincing retinal degeneration by 20 months of age." (PMID 19057657, 2008). "Since usherin is required for maintaining the long term viability of photoreceptors, the absence of usherin from the PMC could be responsible, at least in part, for the late-onset retinal degeneration in whirlin knockout mice." (PMID 20502675, 2010).